KCNQ1 (potassium voltage-gated channel subfamily Q member 1)
Diseases named in the same sentence as KCNQ1 in open-access papers (continued):
Sharing a sentence is not in itself a finding about the gene and the disease.
hearing loss (19 papers, 2011 to 2026). "CpG cites in hearing loss candidate genes, KCNQ1, TMEM43, GSTM1, TCF25, and GSR, were found to be highly methylated in presbycusis patients as compared to the controls." (PMID 40428348, 2025). "Deafness-associated genes KCNQ1 (also associated with heart diseases) and KCNQ4 (only associated with hearing loss) encode the homotetrameric voltage-gated potassium ion channels Kv7.1 and Kv7.4, respectively." (PMID 36140355, 2022). "Several susceptibility genes for hearing loss are involved in potassium recycling, such as connexin genes (GJB2, GJB3), potassium channels or channel subunits (KCNQ1, KCNQ4) and Na+/2Cl-/K+ cotransporter (SLC12A2)." (PMID 39226169, 2024). "In our study, patients with sensorineural hearing loss, seizures, epileptic encephalopathy and cardiomyopathy showed mutations in LOXHD1, KCNQ1, KCNQ2 and MYH7 genes." (PMID 33484326, 2021). "Functional validation is recommended to be carried out in any future study for the variants detected in MYO3A, KCNQ1, PEX6, and TMC1 genes to provide stronger evidence for the pathogenicity of these variants and more robust support for their proposed role in hearing loss." (PMID 40100472, 2025). "However, homozygous carriers without hearing loss have been known since 1998 and may contain a 10% residual KCNQ1 function that rescues hearing." (PMID 29270100, 2017). "In the SV, mutated genes related to ion channels and their regulatory subunits (e.g., KCNE1, KCNQ1 and KCNJ10) may lead to hearing impairment." (PMID 40600354, 2026). "They found that three SNPs in KCNE1, one SNP in KCNQ1, and one SNP in KCNQ4 were significantly associated with noise-induced hearing loss." (PMID 33801540, 2021). "The present study focuses on the identification of the molecular mechanisms of the KCNQ1 variant, p.P631fs*20 (c.1892_1893insC), leading to rare autosomal recessive LQTS without hearing impairment." (PMID 33498651, 2021).
colorectal cancer (15 papers, 2015 to 2024). A primary or metastatic malignant neoplasm that affects the colon or rectum. "Another K+ channel, KCNQ1 (potassium voltage-gated channel subfamily Q Member 1), is also associated with the development of colorectal cancer (CRC)." (PMID 38911514, 2024). "High KCNQ1 expression detected by immunohistochemical staining was found to be associated with the improved OS in a cohort of colorectal cancer patients with liver metastasis." (PMID 38807370, 2024). "KCNQ1 encodes the pore-forming α subunit of voltage-gated potassium channels and they are considered to be a tumor suppressor in colorectal cancer." (PMID 36033489, 2022). "A loss of imprinting of KCNQ1 has been described in colorectal cancer." (PMID 33363037, 2020). "In human colorectal cancer cells that were transferred to the liver, low KCNQ1 protein expression was found to be significantly associated with lower survival, compared with that in patients who demonstrated high KCNQ1 expression, whose survival was approximately 2 years longer." (PMID 36060694, 2022). "An increasing volume of studies have documented the involvement of KCNQ1 in human cancers, including colorectal cancer, hepatocellular carcinoma, esophageal cancer, and renal cell carcinoma." (PMID 35216393, 2022). "Inhibition of the KCNQ1 channels lead to colorectal cancer cell proliferation, EMT and tumorigenesis." (PMID 36033489, 2022). "The identification of the role of the KCNQ1:KCNE3 complex in colorectal cancer has been a major advance in our understanding of molecular mechanisms underpinning sexual dimorphism in CRC tumorigenesis and is discussed in detail in this section." (PMID 33363037, 2020). "Mice carrying a targeted deletion in the KCNQ1 gene developed significantly more intestinal tumors than non-mutant mice, and low expression of KCNQ1 was associated with poor overall survival for colorectal cancer patients." (PMID 39594770, 2024). "Moreover, over-expression of KCNQ1 in the colorectal cancer cell line was found to have trapped β-catenin at the plasma membrane, induced a patent lumen in CRC spheroids, and slowed CRC cell invasion." (PMID 34771544, 2021). "Up until recently, the functional role of the KCNQ1 channel and possible sexual dimorphism in colorectal cancer were unknown." (PMID 33363037, 2020). "KCNQ1 codes for the potassium voltage-gated channel subfamily Q member 1, which has been shown to play important physiological roles in the mammary epithelium and has been suggested to act as a tumor suppressor and regulator of the epithelial–mesenchymal transition in colorectal cancers." (PMID 33113958, 2020).
cardiomyopathy (14 papers, 2015 to 2026). A disease of the heart muscle or myocardium proper. "Five genes account for the majority of genetically explained cardiomyopathy and long QT (MYH7, MYBPC3, KCNQ1, KCNH2, SCN5A), resulting in narrower prediction confidence intervals." (PMID 33046849, 2021).
familial atrial fibrillation (14 papers, 2010 to 2025). An autosomal dominant heart condition that causes disruptions in the heart's normal rhythm. "Mutations in KCNQ1 are associated with familial atrial fibrillation and hereditary long QT syndrome 1 which can impact stroke risk." (PMID 36973604, 2023). "Mutations in KCNQ1 were first identified as being the molecular basis of autosomal dominant atrial fibrillation in a single family from China in 2003." (PMID 23710137, 2013). "It is well known that KCNQ1 gene mutations could result in hereditary long QT syndrome 1, Jervell and Lange-Nielsen syndrome, and familial atrial fibrillation." (PMID 26678516, 2015).
Ventricular arrhythmia (12 papers, 2012 to 2025). "Mutations in KCNQ1 have been identified in human patients with severe ventricular arrhythmia, a long QT interval and slow ventricular repolarization on the ECG signal." (PMID 28702049, 2017). "In addition, the KCNQ1 S140G mutation can induce ventricular arrhythmia and lessen ventricular contractility under re-entrant conditions." (PMID 30108508, 2018). "Consistent with previous studies, our results confirmed the strong relationship between low KCNQ1 protein levels and diminished repolarization reserve, which resulted in triangulation of the action potential and an increased incidence of ventricular arrhythmias after adrenergic stimulation." (PMID 22384037, 2012). "However, the impact of KCNQ1 polymorphisms on the development of ventricular arrhythmias in patients with ischemic cardiomyopathy has not yet been investigated." (PMID 40365780, 2025). "For ventricular arrhythmia, many of the significant proteins identified by the diffusion algorithm are ion channel proteins, such as those that contribute to Ca2+ (CACNA1C, CACNA1C-IT2), Na+ (SCN3A, SCN1B, SCN4B, SCN10A), or K+ (KCNQ1, KCNE3, KCNH2) transport in the heart." (PMID 39954672, 2025).
colon cancer (11 papers, 2018 to 2024). "Among them, KCNQ1 has been implicated as a potential marker in gastric cancer, colon cancer, and breast cancer." (PMID 39317949, 2024). "A study using a transposon approach to identify genes that predisposed to colon cancer revealed KCNQ1 as the 3rd highest hit." (PMID 33363037, 2020). "For example, the downregulation of KCNQ1 expression has been reported to be associated with an inferior survival in colon cancer, and may guide the decision on adjuvant chemotherapy in patients with stage II microsatellite stable colon cancer." (PMID 38807370, 2024). "The concept of KCNQ1 having a role beyond the regulation of cardiac repolarization is further enforced by the finding that KCNQ1 is implicated in the regulation of beta-catenin signaling in colon cancer." (PMID 29740400, 2018). "The role of lncRNA KCNQ1 opposite strand/antisense transcript 1 (KCNQ1OT1) in colon cancer involves various tumorigenic processes and has been studied widely." (PMID 38361755, 2024). "KCNQ1 has been shown to have an antitumorigenic role in many gastrointestinal (GI) cancers, including colon cancer." (PMID 38137047, 2023). "KCNQ1 channels modulate Wnt signalling in a wide number of GI cancers and there is strong evidence for bidirectional interaction between KCNQ1 and β-catenin in normal healthy colon and in colon cancer cells." (PMID 38137047, 2023). "Low or loss of expression of KCNQ1 was previously found to associate with poor disease-free survival in stage II and III colon cancer patients." (PMID 34771544, 2021). "KCNQ1 knockout in a nude mouse model of colon cancer leads to cancer progression, suggesting that KCNQ1 may function as a tumor suppressor." (PMID 36859185, 2023). "KCNQ1 and LVI were identified as key features in prognostic classifiers for disease-free survival in stage II and III colon cancer patients." (PMID 35395779, 2022). "Roles of KCNQ1 opposite strand/antisense transcript 1 (KCNQ1OT1) in cancers including osteosarcoma and colon cancer have been previously reported." (PMID 31909901, 2020). "The results of these classifiers emphasize that KCNQ1 was identified as a strong prognostic biomarker for disease recurrence in both stage II and III colon cancer patients, irrespective of MSI-status and/or treatment with ACT." (PMID 35395779, 2022). "KCNQ1 and lymphovascular invasion were identified as key features in classifiers for prognosis in stage II and III colon cancer patients, either not treated or treated with ACT." (PMID 35395779, 2022).
Insulin resistance (11 papers, 2009 to 2025). Increased resistance towards insulin, that is, diminished effectiveness of insulin in reducing blood glucose levels. "Among numerous genetic loci, TCF7L2 (rs7903146), KCNQ1 (rs2237892), and KCNJ11 (rs5219) are associated with β-cell function, insulin resistance, and insulin action in GDM." (PMID 37107681, 2023). "In addition, KCNQ1-rs2237892 and rs22237897 are associated with MUHO based on insulin resistance or cardiometabolic risk factors." (PMID 40662170, 2025). "This study identifies that KCNQ1 rs2237895 polymorphisms might be associated with risk of GDM in Pakistani population and that it is related to higher glucose levels and insulin resistance." (PMID 28083030, 2016). "This study identifies that KCNQ1 rs2237895 polymorphisms might be associated with risk of GDM in Pakistani population and that it is related to the higher glucose levels and insulin resistance." (PMID 28083030, 2016). "We did not replicate associations with several well-known T2DM genes, including TCF7L2, FTO, IRS1, and KCNQ1, in our Han Chinese population (In our data set, the FTO gene SNPs yielded some associations with insulin resistance related phenotypes in quantitative analyses." (PMID 26139146, 2015). "This suggests that KCNQ1 polymorphism may not have a direct impact on the weight status of an individual but act by other pathways to induce insulin resistance in GDM and/or T2DM." (PMID 28083030, 2016). "Our results suggest that the interplay between the KCNQ1 ACC haplotype and alcohol consumption increases the risk of T2DM resulting from pancreatic β-cell dysfunction, rather than a change in insulin resistance and/or insulin sensitivity." (PMID 34750480, 2021).
gastric cancer (10 papers, 2010 to 2025). A primary or metastatic malignant neoplasm involving the stomach. "Although no expression difference was found between wild-type and mutant KCNQ1 in gastric cancer in some public datasets, the biological functions underlying KCNQ1 mutation need more exploration." (PMID 38807370, 2024). "The results showed that rs10832417G>T in KCNQ1 was associated with improved gastric cancer survival in the whole cohort as well as in some clinical subgroups." (PMID 38807370, 2024). "Collectively, KCNQ1 showed its high progression- and survival-associated potential in gastric cancer based on the data from multiple public datasets." (PMID 38807370, 2024). "The mutation rate of KCNQ1 in gastric cancer was approximately among the average, compared with that in pan-cancers (available online)." (PMID 38807370, 2024). "We deliberately assessed a block of SNPs located in KCNQ1; however, advances in high-throughput technologies may allow for more comprehensive genomic discoveries regarding the associations between genetic variants in KCNQ1 and gastric cancer survival." (PMID 38807370, 2024). "Hence, we used this strategy to investigate the effect of the mutation status of KCNQ1 on its expression in gastric cancer." (PMID 38807370, 2024). "Therefore, future studies on the mutation functions of KCNQ1 in gastric cancer are needed." (PMID 38807370, 2024). "Then, we analyzed the expression profile of KCNQ1 in gastric cancer as well as pan-cancers through various public datasets." (PMID 38807370, 2024). "Long non-coding RNA KCNQ1 is reported to be upregulated in tissues and cells of gastric cancer, functioning as a contributor of gastric cancer." (PMID 35322746, 2022). "The results of the western blot analysis and immunofluorescence showed that KCNQ1 is expressed abundantly in human gastric cancer AGS cells." (PMID 24137337, 2013). "Taken together, these results based on a large population provide solid statistical evidence that KCNQ1 rs10832417G>T may be an independent protector of gastric cancer survival." (PMID 38807370, 2024). "Furthermore, downregulation of the KCNQ1 subunit KCNE2 in gastric cancer inhibits cell proliferation and tumor occurrence in the stomach." (PMID 38370477, 2024). "However, differential expression levels of KCNQ1 were observed among different molecular subtypes of gastric cancer (P < 0.05), with relatively high expression levels in the HM-indel subgroup (available online)." (PMID 38807370, 2024). "We subsequently estimated the prognostic performance of KCNQ1 in meta-datasets from GEO, and consistent results were observed for OS, first progression, and post-progression survival analyses of gastric cancer survival divided by the best cutoff value of its expression levels (available online)." (PMID 38807370, 2024). "The findings of the present study indicate that KCNQ1 rs10832417 may serve as an independent prognostic predictor of gastric cancer, providing novel insights into the progression and survival of the disease." (PMID 38807370, 2024). "Therefore, further biological experiments are needed to identify the potential molecular mechanisms responsible for the survival effects of KCNQ1 and rs10832417 in gastric cancer." (PMID 38807370, 2024). "Furthermore, we observed that gastric cancer patients with downregulated KCNQ1 expression had a poorer survival across multiple public datasets." (PMID 38807370, 2024). "All genes except GPX3, ZBTB16, and KCNQ1 have OR of >1 for gastric cancer, whereas all genes have OR of >1 for Parkinson’s disease, suggesting that for a patient who has either Parkinson’s disease or gastric cancer, the status of 12 genes is highly likely to be un-silenced." (PMID 33596182, 2021). "Because the mutation rates of KCNQ1 in various public datasets were no less than 1% (available online), KCNQ1 mutation may not have a major influence on its expression in gastric cancer (available online)." (PMID 38807370, 2024).
gastric cancer (continued). "Similarly, KCNQ1 rs231348 was reported to be associated with gastric cancer risk in another case-control study but not with gastric cancer survival." (PMID 38807370, 2024). "To better understand the survival effects of KCNQ1 in gastric cancer, we used datasets from TCGA-STAD and GEO to assess the survival probability related to different KCNQ1 expression levels." (PMID 38807370, 2024). "Among the Kv channel family, Kv4.1, Kv7.1 (KCNQ1), and Kv1.5 have been identified as participants in promoting the proliferation and progression of gastric cancer cells." (PMID 38370477, 2024). "In contrast, in human gastric carcinomas, KCNQ1 and KCNE2 expression rarely overlapped, even though KCNQ1 retained its strong co-localization with HKA β." (PMID 20625512, 2010). "There were no significant differential expression levels of KCNQ1 between gastric cancer and adjacent normal tissues (available online) or between gastric cancer and normal stomach samples, including adjacent normal tissues (available online)." (PMID 38807370, 2024).
Hyperglycemia (10 papers, 2011 to 2023). An increased concentration of glucose in the blood. "In comparison with individual datasets, 2 hypomethylated genes (HDAC4 and KCNQ1) were commonly found in the hyperglycemia-treated VAL3 and the Dayeh’s study." (PMID 34639069, 2021). "In vitro and murine studies have shown that the overactivity of the potassium channels from overexpression of KCNQ1 can create a current across the plasma membrane and impair insulin secretion, thereby resulting in hyperglycemia." (PMID 30369944, 2018). "Moreover, the expression levels of mir-1, that has been proved to suppress KCNQ1 and KCNE1 because up-regulated by hyperglycemia, was also evaluated." (PMID 29707106, 2018).
Hypertension (10 papers, 2010 to 2024). The presence of chronic increased pressure in the systemic arterial system. "Also, a genetic variation reducing expression of KCNQ1 in humans correlated with a decreased risk of hypertension, and inhibition of KV7.1 in VSMCs significantly decreased contraction." (PMID 38460127, 2024). "Certain genes involved in the pathogenesis of hypertension—Alb, Chrm2, Xirp1, Kcnq1, Slc5a7, Kcnh1, Ache, Crlf1 and Galr2— should also be studied." (PMID 34603037, 2021). "Taken together, these findings suggest that KCNQ1 mediates the development of hypertension in patients with T2DM." (PMID 26678516, 2015). "It has been documented that Kv7 channels encoded by KCNQ gene family contributed to vasoconstriction and hypertension, which was in concert with the discovery that both C3H/HeJCrl-Kcnq1vtg-2J/J mice and WTC-dfk rats with a KCNQ1 mutation exhibited significantly higher blood pressure." (PMID 26678516, 2015). "Finally, the potassium channels coded by KCNA5 and KCNQ1 can be blocked by quinidine, amiodarone, tedisamil and flecainide (antianginal and antiarrhythmic drugs) or opened by nicorandil (frequently used against hypertension)." (PMID 24165276, 2013). "Therefore, our data support that KCNQ1 is associated with an increased risk for T2DM and might contribute to the higher incidence of hypertension and macrovascular complications in patients with T2DM carrying the risk allele C though it needs further to be confirmed in a larger population." (PMID 26678516, 2015).